MIR4699 (microRNA 4699)
Synonyms: hsa-mir-4699
Gene: MicroRNA gene on chromosome 12 (81,158,388 to 81,158,461, forward strand). Ensembl gene ENSG00000265227.
Homologues: Orthologues: chimpanzee MIR4699 (100% identical).